KLF1 (KLF transcription factor 1)
Diseases named in the same sentence as KLF1 in open-access papers (continued):
Sharing a sentence is not in itself a finding about the gene and the disease.
tumor (14 papers, 2020 to 2026). "One tumor-associated cluster (HBB+/ALAS2+) expressed high levels of erythroid progenitor genes (KLF1) and was highly proliferative, which we annotated as tumor-associated erythroid cells." (PMID 36008377, 2022). "We next investigated whether KLF1(K74R) knockin attenuated the incidence of spontaneous neoplasia, the commonest cause of death in laboratory mice at the end of life." (PMID 35822667, 2022). "Our study demonstrates a significant upregulation of KLF1 expression in tumour samples from HCC patients compared to normal liver tissue, with higher expression levels strongly correlating with poorer survival outcomes." (PMID 41656392, 2026). "Overall, KLF1 silencing downregulated the LINC02159/DYNC1H1 pathway to inhibit tumor growth in vivo." (PMID 40798857, 2025). "KLF1 silencing led to decreased tumor volume and weight (p < 0.01) and decreased the Ki67‐positive rate of proliferation (p < 0.01)." (PMID 40798857, 2025). "As shown, tumor growth in mice subjected to BMT from Klf1(K74R) mice was significantly slower relative to those receiving BMMNC from WT mice." (PMID 38752723, 2024). "The curves of tumor growth started to show difference between the Klf1(K74R) and WT mice at 49 d after Hepa1-6 cell injection." (PMID 38752723, 2024). "Consistently, the LLC and EL4 inoculated Klf1K74R/K74R mice exhibited a reduction in tumor growth compared to Klf1+/+ mice (0.17 ± 0.05 g vs 0.50 ± 0.11 g, p < 0.01; 460 ± 65 cm3 vs 156.56 ± 46.35 cm3, p < 0.05 and 0.33 ± 0.16 g vs 1.03 ± 0.66 g." (PMID 35822667, 2022). "VIRMA could stabilize KLF1 mRNA, upregulate KLF1 expression, and consequently enhance PD-L1 expression and promote immune evasion by tumor cells." (PMID 40723784, 2025). "Additionally, VIRMA facilitates immune evasion within the tumor microenvironment via the KLF1-PD-L1 signaling axis." (PMID 40723784, 2025). "KLF1 silencing inhibited tumor growth in vivo by downregulating the LINC02159\DYNC1H1 pathway." (PMID 40798857, 2025). "(B) Pulmonary tumor foci assay of 24-month-old WT and Klf1(K74R) male mice." (PMID 38752723, 2024). "To determine whether Klf1(K74R) BMT could inhibit tumor growth, we examined the effects of BMT on growth of tumors with B16-F10-luc cells." (PMID 38752723, 2024). "Furthermore, our experiments demonstrated that RBM15 downregulation significantly inhibited lung and liver metastasis of tumor cells, while KLF1 overexpression and TRIM13 downregulation significantly promoted lung and liver metastasis (p < 0.05)." (PMID 39716068, 2024). "However, in our study, we found that upregulating KLF1 led to increased tumor growth, enhanced proliferation capacity, and promoted lung metastasis and liver metastasis in NSCLC cancer cells." (PMID 39716068, 2024). "A comparison of tumor growth rate and tumor size after inoculation showed tumor growth was markedly delayed in Klf1K74R/K74R mice, while tumor weight was significantly lower than that in Klf1+/+ mice (0.10 ± 0.04 g vs 0.67 ± 0.14 g, p < 0.01)." (PMID 35822667, 2022). "Furthermore, the KLF1(K74R) knockin affects a subset of lymphoid lineage cells; the abundance of tumor infiltrating effector CD8+ T cells and NKT cells is increased resulting in antitumor immune enhancement in response to tumor cell administration." (PMID 35822667, 2022). "Notably, high cancer incidence was observed in aged Klf1+/+ mice with a spontaneous tumor incidence of 75%, while the Klf1K74R/K74R mice were found to be considerably resistant to tumorigenesis (about 12.5%)." (PMID 35822667, 2022). "Further mechanistic investigations reveal that KLF1 inhibits ACSL4 expression via transcriptional repression and suppresses ferroptosis through the ACSL4/LPCAT3 axis, ultimately promoting HCC tumour growth as well as its advancement." (PMID 41656392, 2026).
tumor (continued). "Analysis of tumor tissues showed significant downregulation of RBM15, KLF1, and ANXA8, along with reduced m6A content (p < 0.01), while TRIM13 expression was increased (p < 0.01) in the sh-RBM15 group compared to the sh-NC group." (PMID 39716068, 2024). "Through transcription factor analysis, we can see that State7, 6, 5, 3, representing tumours, is enriched in STAT5B, TFAP2C, KLF1, ZBTB7A, etc.." (PMID 38613345, 2024). "The decreased expression levels of WNT1, cytoplasmic and nuclear β-catenin, and downstream targets c-Myc and cyclin D1 suggest that KLF1 promotes the proliferation and EMT progression of tumor cells by activating this signaling pathway." (PMID 36761967, 2023). "KLF1, KLF5, and KLF8 promote tumor proliferation by activating the expression of the WNT/β-catenin pathway." (PMID 36761967, 2023). "In contrast, KLF1 overexpression and TRIM13 downregulation accelerated tumor growth (p < 0.05)." (PMID 39716068, 2024). "In the current study, we demonstrate that the healthy longevity of the Klf1(K74R) mice, as exemplified by their higher tumor resistance, is likely to be gender/genetic background independent and irrespective of the amino acid change at K74 of KLF1." (PMID 38752723, 2024). "However, similar to Klf1(K74R) mice challenged with B16-F10 cells, WT mice that received BMMNC from Klf1(K74R) mice presented significantly fewer tumor foci on their lungs." (PMID 38752723, 2024).
cancer (11 papers, 2017 to 2025). A tumor composed of atypical neoplastic, often pleomorphic cells that invade other tissues. "Overall, strongly expressed KLF1 could be recognized as a risk manifestation in human cancers." (PMID 40798857, 2025). "Furthermore, we show that the higher anti-cancer capability and extended lifespan of Klf1(K74R) mice are associated with changes in the global protein expression profile and specific aging-/cancer-associated cellular signaling pathways in their white blood cells (WBCs) or leukocytes." (PMID 38752723, 2024). "Thus, transplantation/transfer of the blood MNC carrying homozygous mutation at the sumoylation site of KLF1 could be developed as a new approach for long-term anti-aging, anti-cancer, and likely rejuvenation." (PMID 38752723, 2024). "It thus appears that the Klf1(K74R) mice are resistant to the carcinogenesis of a range of different cancers." (PMID 38752723, 2024). "In summary, we have characterized the cancer resistance of the Klf1(K74R) mice, among their other healthy characteristics, in relation to gender, age, and genetic background." (PMID 38752723, 2024). "The anti-cancer capability of the Klf1(K74R) mice has rendered them relatively free from spontaneous cancer occurrence, which is also reflected by their resistance to tumorigenesis of the B16-F10 cells and Hepa1-6 in the anti-cancer assays." (PMID 38752723, 2024). "Transfer of cancer resistance of Klf1(K74R) mice to wild-type (WT) mice by bone marrow transplantation (BMT)." (PMID 38752723, 2024). "We first used RT-qPCR to analyze the levels in PB cells of mRNAs encoding the immune checkpoint genes (ICGs) PDCD/CD274 in view of the cancer resistance of Klf1(K74R) mice as well as increased levels of PDCD and CD274 in aged or tumorigenic mice." (PMID 38752723, 2024). "The Klf1(K74R) mice appeared to be cancer resistant to carcinogenesis as manifested by their lower spontaneous cancer incidence (12.5%) in life than WT mice (75%)." (PMID 38752723, 2024). "The lower expression of ICGs would contribute to the anti-cancer capabilities of the Klf1(K74R) blood to fight against cancer and to extension of the lifespan of cancer-bearing mice." (PMID 38752723, 2024). "We show that the healthy longevity characteristics of the Klf1(K74R) mice, as exemplified by their higher anti-cancer capability, are likely gender-, age-, and genetic background-independent." (PMID 38752723, 2024). "Secondly, homozygosity of the K74R substitution was required for the higher cancer resistance of the Klf1(K74R) mice." (PMID 38752723, 2024). "We tested the in vitro cancer cell cytotoxicity ability of NK(K74R) cells from 3-month-old Klf1(K74R) mice in comparison to the WT NK cells." (PMID 38752723, 2024). "As described in the following, we have since characterized the high anti-cancer capability of the Klf1(K74R) mice with respect to its dependence on the age, gender, and genetic background." (PMID 38752723, 2024). "On the other hand, the level of IL-6, a key factor in chronic inflammatory diseases, autoimmunity, cytokine storm, and cancer, increased only moderately during aging of the Klf1(K74R) mice." (PMID 38752723, 2024). "The motifs of the Kruppel-like factor subfamily genes such as KLF1/3/4/5/6/14 were specifically enriched in the NDRs in the cancer cells." (PMID 35165277, 2022). "Some studies revealed that Krüppel-like factor 1 (KLF1) promoted the proliferation and invasion of multiple types of cancer cells." (PMID 34304709, 2021). "Thus, even at a low level of 20% blood replacement, BMT still enabled effective transfer of cancer resistance from Klf1(K74R) mice to WT mice." (PMID 38752723, 2024). "The higher anti-cancer capability of the Klf1(K74R) mice could result from combined contributions by different types of the hematopoietic cells, for example, the NK(K74R) cells." (PMID 38752723, 2024).
cancer (continued). "Notably, KLF1 is implicated in the M2 polarization of macrophages in NSCLC, facilitating metastasis and the EMT process in these cancer cells." (PMID 39716068, 2024). "In order to determine whether WT mice having more restricted blood replacement upon BMT from Klf1(K74R) mice still exhibited a higher anti-cancer capability, we also carried out BMT experiments with lower doses of γ-irradiation." (PMID 38752723, 2024). "Targeted/global gene expression profiling analysis has identified changes in the expression of specific proteins, including the immune checkpoint factors PDCD and CD274, and cellular pathways in the leukocytes of the Klf1(K74R) that are in the directions of anti-cancer and/or anti-aging." (PMID 38752723, 2024). "Since KLF1 is a hematopoietic transcription factor expressed not only in mature blood cells but also in HSCs and hematopoietic stem progenitor cells, this cancer resistance may be transferable by means of BMT." (PMID 38752723, 2024). "Thus, similar to PDCD and CD274, the altered expression of some of the cytokines in the blood likely also contributes to the anti-aging and/or anti-cancer characteristics of the Klf1(K74R) mice." (PMID 38752723, 2024). "Importantly, we have shown that the anti-cancer capability and the extended lifespan characteristics of Klf1(K74R) mice are transferrable through BMT." (PMID 38752723, 2024). "Furthermore, the Klf1(K74R) mice appeared to have significantly higher anti-cancer capability than the WT mice." (PMID 38752723, 2024). "In aged Klf1K74R/K74R mice, the lower cancer incidence and mild alteration in myeloid and lymphoid commitment imply that KLF1(K74R) knockin mediated lifespan extension and healthy aging may be relevant to the presence of effective cellular immunity." (PMID 35822667, 2022). "In NSCLC cancer tissues, RBM15 expression was positively correlated with KLF1 and negatively correlated with TRIM13 (p < 0.01)." (PMID 39716068, 2024). "Similar observations were made for EPOR and KLF1; both genes showed significant co-expression with GATA2 and positive GATA2 binding observed for multiple cancer cell lines in ChIP-seq experiments." (PMID 35087776, 2021). "In NSCLC, RBM15 up-regulates Kruppel-like factor 1 (KLF1), which suppresses the expression of TRIM13, a member of the tripartite motif (TRIM) family, and promotes ANXA8, a member of the annexin A (ANXA) family, thereby accelerating cancer progression." (PMID 41256854, 2025). "A genetically engineered mouse model, termed Klf1K74R/K74R or Klf1(K74R), carrying mutation on the well-conserved sumoylation site of the hematopoietic transcription factor KLF1/EKLF has been generated that possesses extended lifespan and healthy characteristics, including cancer resistance." (PMID 38752723, 2024). "In particular, the decreasing cancer incidence in Klf1K74R/K74R mice, also seen in the FMD treatment, is most likely due to KLF1(K74R) influencing reprogramming of the immune‐modulatory cascades of hematopoietic/blood system and improvement in CD8+ T‐cells and NKT cell infiltration." (PMID 35822667, 2022). "The anti-metastasis property of the Klf1(K74A) mice in the pulmonary foci assay also indicates that the anti-cancer capability of the Klf1(K74R) mice is not due to the structural and/or post-translational properties of the arginine introduced at codon 74 of KLF1." (PMID 38752723, 2024). "Importantly, the Klf1(K74R) mice in the FVB background also exhibited a high cancer resistance than FVB WT mice by this assay, suggesting that cancer resistance of Klf1(K74R) mice conferred by the homozygous K74R substitution was likely genetic background-independent." (PMID 38752723, 2024). "Furthermore, the cancer resistance of Klf1(K74R) mice appears to be independent of the gender, age, and genetic background." (PMID 38752723, 2024).
cancer (continued). "Finally, the higher anti-cancer capability of the Klf1(K74R) mice did not appear to depend on the arginine at codon 74 since Klf1(K74A) mice carrying K→A amino acid substitution at the K74 sumoylation site also exhibited higher anti-metastasis capability than WT mice in the pulmonary foci assay." (PMID 38752723, 2024).
blood cancers (1 paper, 2018). "We finally considered whether variation in levels of KLF1, rather than a mutated form, might be correlated with a particular blood cancer." (PMID 29700354, 2018).
heart disease (1 paper, 2025). "Furthermore, given the widespread application prospects of adeno‐associated virus (AAV)‐mediated gene therapy in the study of heart disease, we overexpressed KLF1 in cardiomyocytes." (PMID 40145861, 2025).
KLF1 also shares sentences with these, for which no sentence is quoted: erythroleukemia (3 papers); Iron deficiency anemia (3); acute erythroleukemia (2); diabetes (2); infection (2); Thrombocytosis (2); acute myeloid leukemia (1); autosomal dominant disease (1); breast tumors (1); chronic myelogenous leukemia (1); congenital anemia (1); dyslipidemia (1); epilepsy (1); erythroid neoplasm (1); glioblastoma (1); glioma (1); Hepatic fibrosis (1); Immune Deficiency (1); Infertility (1); Intellectual disability (1); iron deficiency (1); ischemia (1); maturity-onset diabetes (1); Obesity (1); osteoporosis (1); pancreatic cancer (1); Parkinson disease (1); schistosomiasis (1); Spherocytosis (1); T-cell acute lymphoblastic leukemia (1).
A further 4 diseases each share a sentence with KLF1 in 1 paper.